IL6 (interleukin 6)
Diseases named in the same sentence as IL6 in open-access papers (continued):
Sharing a sentence is not in itself a finding about the gene and the disease.
COVID-19 (continued). "IL-6 is a proinflammatory cytokine that can stimulate the release of other cytokines and activate immune cells, contributing to the overall systemic inflammation observed in severe COVID-19 cases." (PMID 36901751, 2023). "IL-6 was deemed as a prognostic factor and potential treatment target of severe COVID-19 cases." (PMID 37384050, 2023). "In COVID-19 patients, IL-6 levels are significantly elevated, so serum IL-6 was used as a biomarker of COVID-19 severity and to decide on the administration of immunosuppressive treatment for the famous cytokine storm, based on experience in rheumatological and autoimmune diseases." (PMID 36836567, 2023). "The breakdown of the BBB triggers a severe inflammatory response, causing the cytokine storm (release of IL-1β, IL-6, TNF-α, etc.)characteristic of the severe phase of COVID-19, which includes the recruitment of macrophages and lymphocytes and the activation of astrocytes and microglia." (PMID 36998270, 2023). "Age, IgG, and IL6 could potentially serve as useful predictors for nucleic acid clearance exceeding 14 days in asymptomatic and mild COVID-19 patients." (PMID 38125571, 2023). "IL-6 is a prognostic and therapeutic target for COVID-19 patients." (PMID 38155729, 2023). "In conclusion, we identified that patients with critical COVID-19 could be divided into two groups with different degrees of cytokinemia and T-cell responses, according to their serum IL-6 levels." (PMID 37081872, 2023). "The results of this study are expected to provide information regarding the body’s immune response and inflammation in COVID-19, which is characterised by differences in serum levels of the pro-inflammatory cytokine IL-6 and an imbalance of inflammatory cells with the NLR." (PMID 38099004, 2023). "A study showed that the IL-6/IL-10 ratio is a more ideal prognosis biomarker for COVID-19." (PMID 36914565, 2023). "However, only IL-6 showed a significant and stepwise increase between these subgroups in non-COVID-19 patients (each p < 0.05), opposite to DPP3 and leucocytes (each p = n.s)." (PMID 37733154, 2023). "IL-6, which is often elevated in COVID-19 and related to severity, seems to be the pro-inflammatory cytokine most implicated, perhaps because this cytokine often acts in a more endocrine manner than others, acting on target cells at a distance, following transportation through the bloodstream." (PMID 37560297, 2023). "In detail, this study revealed increased levels of IL-6 and reduced levels of miR-146a-5p in COVID-19 patients compared to healthy age-matched control subjects, highlighting the role of the imbalance between IL-6 and miR-146a-5p in the pathogenesis of COVID-19." (PMID 36768701, 2023). "The forest plot showed high levels of IL-6 for long COVID-19 compared with healthy controls (mean difference = 9.75 pg/ml, 95% CI = 5.75–13.75 pg/ml, I2 = 100%, P < 0.00001) and PASC category (mean difference = 3.32 pg/ml, 95% CI = 0.22–6.42 pg/ml, I2 = 88%, P = 0.04)." (PMID 37095536, 2023). "In our study, NLR was an independent predictor of mortality in obese patients;1 probably because it reflects the inflammatory severity of COVID-19 added to the chronic inflammation of these patients (previously demonstrated by greater levels of IL-6 and CRP in the blood)." (PMID 37024861, 2023). "As a result, the cytokine storm in SARS/COVID-19 may be a key mediated by IL-6 and GM-CSF secreted by mononuclear and T lymphocyte cells." (PMID 37124230, 2023). "It has been postulated that IL-6 plays a critical role in virus-induced cytokine storm, hence, a recombinant humanized monoclonal antibody IL-6 receptor inhibitor, tocilizumab, has recently emerged as an alternative treatment for COVID-19." (PMID 37629728, 2023). "CGRP is known to enhance interleukin-6 production, the main biomarker of COVID-19 severity, which has even brought the proposal that CGRP antagonists could be of help in COVID-19 infection." (PMID 36932352, 2023).
COVID-19 (continued). "Cocultures with M-MDSC had high levels of Arg1, the suppressive effect of M-MDSC on T cell proliferation was reduced by the addition of L-Arginine, and plasma levels of Arg-1 and IL-6 were elevated in COVID-19 patients, which increased with increasing severity of disease." (PMID 37545508, 2023). "Their results and further studies on how HOCl and HOBr and their halogenated amine derivates interact with IL-6 may open alternative therapeutic interventions in COVID-19 and other hyperinflammatory diseases." (PMID 37034111, 2023). "Thus, it can be assumed that constant antigenic and cytokine (IL-6) stimulation seems to reduce the expression of the NKG2D receptor not only on NK cells but also on T cells during COVID-19." (PMID 37240393, 2023). "This is most seen for IL-6 – the most widely studied cytokine in acute COVID-19 - where using a highly sensitive assay reporting results to the femtogram, we see similar results across disease severity categories – with levels much lower than that typically seen in CRS." (PMID 37063871, 2023). "In addition to SSc, the relationship between IL-6 and lung fibrosis was observed in other diseases as well, such as COVID-19-induced respiratory failure." (PMID 37833885, 2023). "Of note, among elevated inflammatory mediators, blood IL-6 levels, known as the IL-6 amplifier, correlate highly with the lethal complications of COVID-19, suggesting that fatal COVID-19 can be characterized as a cytokine release syndrome (CRS) induced by a cytokine storm, with high mortality." (PMID 36635345, 2023). "Similarly, PD-L1, ILT-3 and IDO-1-expressing M-MDSC were the dominant producers of IL-10 and IL-6 in severe COVID-19 patients, and this correlated with increased inflammatory markers, as well as accumulation of regulatory T and B cells." (PMID 37545508, 2023). "In cells directly infected by SARS-CoV-2, the NOTCH pathway might promote viral entry, and in addition, excessive NOTCH signaling may promote interleukin 6 (IL-6) and inflammatory pathways that can exacerbate the morbidity and severity of COVID-19." (PMID 37834236, 2023). "A previous study found that IL-6 serum level was significantly increased in COVID-19 children." (PMID 37889917, 2023). "Except for IgG 1/IgG 4, LY #, and HGB, the severe COVID-19 group exhibited significantly elevated levels of IL-2, IL-6, IgG 2/IgG 1, IgG Sum/IgG 1, IgG 2/IgG Sum, CRP, PT, INR, DD, WBC, NE #, NLR, RDW, and PDW in comparison to the non-severe COVID-19 group (p<0.05)." (PMID 38106427, 2023). "Indeed, nearly every study with IL-6 data from COVID-19 patients demonstrates levels that correlate with and predict worsening disease outcomes 3, 7, 9, 33, 45]." (PMID 37427016, 2023). "IL6 may participate in myocardial injury through the interleukin signaling pathway in COVID-19 patients." (PMID 37564653, 2023). "The limitation of our study is that only one cytokine (IL-6) was studied to define COVID-19 CS." (PMID 34866562, 2023). "We aimed to evaluate the efficacy and safety of ixekizumab (IL-17 inhibitor), low-dose IL-2, and colchicine (indirect IL-6 inhibitor) combined with SOC treatment in comparison with SOC alone for the treatment of hospitalized patients with moderate-to-critical COVID-19." (PMID 37075454, 2023). "Similarly, after some controversy, the same occurred with the indication of tocilizumab (IL-6 inhibitor agent) in severe cases of COVID-19." (PMID 37515137, 2023). "Furthermore, anti-spike IgG isolated from hospitalized COVID-19 patients contained lowered core-fucose levels in severe patients, promoting macrophage release of IL-6 and TNF-α and the destruction of endothelial barriers in vitro by binding FcγR IIA and IIIA." (PMID 37398192, 2023). "The sharp increase in IL-6 levels during acute infection is due to a cytokine storm, while it might decrease due to the different dynamic changes in IL-6 and antibodies during the long COVID-19 phase." (PMID 37095536, 2023).
COVID-19 (continued). "We found elevated pre-pandemic IL-6 levels increased the risk of developing fatigue in adult volunteers who had never had COVID-19; however, pre-pandemic IL-6 levels did not predict fatigue in our COVID-19-positive group." (PMID 36995412, 2023). "However, in experimental studies of COVID-19, the production of IL-6 in blood serum and bronchoalveolar lavage fluid of hamsters was not shown." (PMID 37520568, 2023). "These associations may be due to residual confounding, in that people with diabetes or who received IL-6 inhibitors might represent sub-populations with more severe COVID-19 who thus might stay in hospital for longer, leading to increased antibiotic use." (PMID 36736332, 2023). "The main finding of our study is that in mechanically ventilated patients admitted to the ICU with severe COVID-19 in low-resource settings and living at high altitude, low-cost and immediately available blood biomarkers such as IL-6 and NLR can predict mortality in the ICU." (PMID 36675573, 2023). "Elevated levels of CXCL10 and IL-6 has been shown to correlate with severe COVID-19." (PMID 37507719, 2023). "According to recent studies, the secretion of cytokines, such as interleukin (IL)-1β, IL6, and IL-10, and mediators such as TNF-α have been significantly stimulated in patients with COVID-19 and are associated with rapid disease progression in high-risk patients." (PMID 37047078, 2023). "Contrarily, patients with COVID-19 who were severely infected experienced an excessive release of cytokines and chemokines, such as interleukin (IL)-1, IL-2, IL-6, IL-7, IL-8, IL-10, granulocyte-colony stimulating factor (GCSF), and tumour necrosis factor-alpha (TNF-α)." (PMID 36679947, 2023). "The levels of Nrf2, HO-1, NFκB, and IL-6 were higher in the granulocytes of COVID-19 patients who died within a week, while the activity of cytoplasmic Cu,Zn-SOD and mitochondrial Mn-SOD and IL-2/IL-10 were lower in comparison to the levels observed in survivors." (PMID 37686388, 2023). "IL-6 has already been predicted as a useful biomarker in managing COVID-19." (PMID 36926338, 2023). "The cytokine storm in COVID-19 suggested that IL-6 might be useful as prognostic biomarker, hence medical research investigated this question." (PMID 37391718, 2023). "Hyperactivation of the immune response, including the release of pro-inflammatory cytokines such as interleukin-6 (IL-6), plays a key role in the pathophysiology of severe COVID-19 since IL-6 promotes endothelial dysfunction and the development of vascular permeability." (PMID 37324114, 2023). "Therefore, it is likely that the positive clinical effects of anakinra and tocilizumab in patients with severe COVID-19 are due to their ability to block the systemic inflammation induced by IL-1 and IL-6, respectively." (PMID 36651846, 2023). "Recent studies have indicated that severe COVID-19 patients with lower inflammatory interleukin-6 (IL-6) levels may exhibit improved prognosis." (PMID 37598150, 2023). "Tocilizumab (ROACTEMRA©) was considered since compelling data suggested that IL-6 could be a key cytokine in COVID-19 pathophysiology, and that drugs targeting IL-6 such as tocilizumab are an appealing therapeutic strategy." (PMID 37510786, 2023). "IL-6 is a biomarker in sepsis, respiratory infection, and COVID-19." (PMID 37733154, 2023). "Additionally, the importance of NF-kB-dependent cytokine and chemokine production in severe/critical COVID-19 has been consistently reported – with many studies examining Interleukin (IL)-6 in plasma as a critical predictor of COVID-19 severity and mortality." (PMID 37063871, 2023). "The regulation of inflammatory mediators, such as TNF-α, IL-6, IL-1β, and leukotriene B4, could play a crucial role in suppressing inflammatory diseases such as COVID-19." (PMID 36611603, 2023).
COVID-19 (continued). "In addition, we assessed the inflammatory status of patients by monitoring only CRP values without measuring levels of cytokines with a recognized role in COVID-19, such as IL-6." (PMID 37959277, 2023). "However, using a random coefficient model, we detected a possible association between increased disease activity and COVID-19 vaccination in patients treated with JAK-i, IL-6-i or IL-12/23-i." (PMID 36927849, 2023). "COVID-19 and these levels of IL-6 are positively correlated with the detection of viral RNA." (PMID 37180105, 2023). "Indeed, owing to its primary role in triggering the cytokine storm in COVID-19, the higher plasma level of IL-6 is considered as a significant marker of worse disease prognosis in COVID-19 infected patients." (PMID 36794069, 2023). "Indeed, a large meta-analysis of cytokine measurements in ARDS patients of different causes revealed lower levels of inflammatory markers, such as IL-6 and TNF-α, in COVID-19-associated ARDS." (PMID 37283766, 2023). "However, even 2–3 months after recovering from COVID-19, alterations in the levels of both pro-inflammatory cytokines, such as IL-1β, IL-6, TNFα, and the anti-inflammatory cytokine IL-10, have been observed in semen." (PMID 37958725, 2023). "Besides ferritin and IL-6, other commonly used inflammatory biomarkers are important in monitoring COVID-19 patients." (PMID 37754237, 2023). "The consistent elevation of IL-6 in severe COVID-19 made it an attractive target for intervention, especially given the success of anti-IL-6 agents in other cytokine release syndrome conditions such as in reactions to chimeric antigen receptor (CAR)-T-cell therapy." (PMID 37427016, 2023). "Pro-inflammatory cytokines such as IL-1, IL-10, IL-6, and TNF- α were found in significant concentrations in COVID-19 individuals, causing a cytokine storm during SARS-CoV-2 infection, which has been linked to ARDS, multi-organ failure, and increased candidate risk." (PMID 36608055, 2023). "Inhibition of IL-6 may be a novel target for therapies for the control of dysregulated host responses in patients with COVID-19." (PMID 37504277, 2023). "This inhibits the pro-inflammatory activity of IL-6, which may be increased in patients with COVID-19." (PMID 37445553, 2023). "Numerous studies have shown that markers such as IL6 and CXCL8/IL8, as well as certain patterns in multiomics-based studies, might be associated with COVID-19 severity and lethality." (PMID 37310504, 2023). "Sarilumab is another type of IL-6R inhibitor studied in SARS-CoV-2, which could indicate a potential therapeutic advantage of early intervention with IL-6-modulatory COVID-19 treatments." (PMID 37124230, 2023). "In another study, transplantation of MSCs in COVID-19 patients was associated with a significant increase in anti-inflammatory cytokines (IL-10, IL-13) and also a significant decrease in pro-inflammatory cytokines, i.e., IFN-γ, IL-6." (PMID 37365605, 2023). "IL-6, an important pro-inflammatory factor, is associated with high SARS-CoV-2-induced inflammatory responses as well as a predictor of disease severity in COVID-19 patients." (PMID 38274101, 2023). "In the same line, miR-200a-3p overexpression downregulates SOCS-6, also a JAK–STAT regulator, and in COVID-19 patients this miRNA is in fact overexpressed; moreover, miR-200c-3p is positively correlated with IL-6 levels and in one study included in the review this miRNA was overexpressed." (PMID 36834984, 2023). "Indeed, a cytokine storm had been observed in severely ill COVID-19 patients, and most of these patients exhibited markedly increased serum levels of proinflammatory cytokines, such as interleukin (IL)-6, tumor necrosis factor alpha (TNF-α), GM-CSF, and IL-1β." (PMID 37762435, 2023).
COVID-19 (continued). "Numerous clinical studies have also revealed that elevated amounts of IL-10 in the serum of COVID-19 patients, alone or with IL-6, IL-12 or IL-1RA, may accurately predict progression to more severe form of disease and increased mortality." (PMID 37359549, 2023). "Besides IL-6 and LDH, other laboratory parameters are cited in the literature as independent risk factors of death in COVID-19, such as neutrophil count, platelet count, CRP, D-dimers, troponin-I and low total testosterone." (PMID 36836679, 2023). "Finally, we showed a positive correlation of endostatin with soluble disease markers VE-Cadherin, c-reactive protein (CRP), fibrinogen, and interleukin (IL)-6 in our COVID-19 cohort." (PMID 37283766, 2023). "Second, some inflammatory markers associated with critical cases of COVID-19, such as IL-6, interleukin (IL)-1β, and TNF-α, were not included." (PMID 36999038, 2023). "There is increasing evidence for the relevance of IL-6 as a prognostic marker for COVID-19." (PMID 38264533, 2023). "IL-6 has been considered as a biomarker in the progression and development of COVID-19." (PMID 37376569, 2023). "This study showed that increased IL-6 correlates with long COVID-19." (PMID 37095536, 2023). "In addition, the identification of elevated IL-6 levels in serum as a strong predictor of respiratory failure in patients with COVID-19 makes IL-6 one of the critical cytokines in the COVID-19–related hyperinflammatory syndrome." (PMID 36776881, 2023). "IL-6 is one of the main cytokines involved in COVID-19 pathogenesis." (PMID 37886013, 2023). "Thus, our study suggests IL6/IL6R signaling as a plausible ‘downstream’ therapeutic target in IFNB1-overexpressing patients with COVID-19, which should be investigated in future clinical trials." (PMID 37217661, 2023). "Additionally, in a study on cytokine profiles in acute COVID-19 and long COVID-19 syndrome, Queiroz and colleagues reported that IL-6 is one of the important cytokines that is relevant to the outcome of COVID-19, including disease duration and severity." (PMID 37095536, 2023). "In particular, in COVID-19 patients, a meta-analysis showed that patients with sufficient vitamin D had significantly lower levels of interleukin-6, C-reactive protein, ferritin, lactate dehydrogenase, fibrinogen, and D-dimer compared to those in the vitamin D deficient group." (PMID 36829806, 2023). "The aim of the current prospective cohort study in this context is to assess how the severity of symptoms and the outcome of COVID-19 can be controlled and improved when IL-1 antagonist anakinra and IL-6 antagonist tocilizumab are prescribed early to individuals with mild to moderate cases." (PMID 37046952, 2023). "Notably, some COVID-19 convalescents possess elevated blood levels of IL-6, although the significance of these findings in MDSC development and long-COVID has not been completely resolved." (PMID 38257728, 2023). "The pro-inflammatory environment and the triad of high systemic levels of IP-10, IL-10, and IL-6 depicted in severe patients from the first COVID-19 wave from Argentina have been reported in other cohorts, also occurring with a reduced frequency of circulating Treg." (PMID 37809093, 2023). "This study, which encompassed 130 confirmed COVID-19 patients who were assessed at three different time points (i.e., 3, 7, and 12 days) after the onset of symptoms, investigated interleukin-6 (IL-6) enhancement induced by a viral nucleocapsid (N) protein from a myeloid cell line." (PMID 37896795, 2023). "It has been hypothesized that death from COVID-19 may be associated with immunogenetic markers including IL12B, along with HLA-B, IL6, and IL10." (PMID 36800980, 2023). "COVID-19 patients have elevated levels of inflammatory cytokines, particularly IL-6." (PMID 38155729, 2023).